NPC1 (NPC intracellular cholesterol transporter 1)
Diseases named in the same sentence as NPC1 in open-access papers (continued):
Sharing a sentence is not in itself a finding about the gene and the disease.
neurological disease (27 papers, 2011 to 2026). "NPD type C is a neurologic disorder due to mutations in the genes NPC1 or NPC2, causing a defect of cholesterol trafficking and esterification." (PMID 38397448, 2024). "Within the last few years, a series of studies showed that the progress of neurologic disease in NPC1-deficient mice is slowed down by intra-cardiac, intra-cisternal, and intra-cerebroventricular injection of vectors based on adeno-associated virus 9 (AAV9)." (PMID 33256121, 2020). "In this case, NPC1 mutation analysis was only applied after the appearance of neurological disorders, and it identified known mutations allowing a full confirmation of the diagnosis." (PMID 27250337, 2016). "However, NPD type C is a neurological disorder caused by mutations in the NPC1 or NPC2 genes, leading to defects in cholesterol trafficking and esterification." (PMID 38397448, 2024). "Combining these observations with the data showing an attenuated neurological disease phenotype in double-mutant Soat1-/-:Npc1-/- mice, we hypothesized that the rs1044925 A-allele could be a genetic modifier of the NPC1 phenotype in individuals with NPC1." (PMID 38673803, 2024). "However, in vivo studies showed that the drug slows down neurologic disease progression and prolongs the life span of NPC1-deficient BALB/c mice and NPC1 mutant cats, providing preclinical evidence for its therapeutic use." (PMID 33256121, 2020). "A subset of subjects with heterozygous NPC1 gene mutation may be more susceptible to neurological disorders." (PMID 31497485, 2019). "Furthermore, intrathecal administration of CD in a feline model harboring a missense mutation in NPC1 has recently been shown to better ameliorate aspects of the neurological disease and extend lifespan when compared to systemic injection." (PMID 22073306, 2011). "Our data presented here are congruent with the notion that serum NfL can be used as a biomarker for NPC1 neurological disease progression and therapeutic intervention." (PMID 40821948, 2025). "The age of NPC1 neurological disease onset and disease severity is highly variable, ranging from infancy to adulthood." (PMID 40821948, 2025). "A murine model of NPC1 (Npc1−/−, BALB/cNctr-Npc1m1N/J) carries a spontaneous loss of function mutation in the Npc1 gene and develops classical NPC neurological disease, including the loss of Purkinje cells and an almost disease-free spinal cord." (PMID 36519759, 2023). "Our adapted phenotypic scoring system is applicable to murine models of NPC1 and likely other models of neurological disorders with ataxic phenotypes." (PMID 35452076, 2022). "The findings in which the accumulation of cholesterol was ameliorated and motor function was improved in NPC1-mutant mice suggest that intranasally delivered hUCB-MSCs have a therapeutic effect on neurological disorders." (PMID 30429460, 2018). "Our data suggest a positive correlation between NPC1 neurological disease severity and assembly of the necrosome complex." (PMID 26986514, 2016). "The LysoTracker® signal was significantly elevated in NPC1 patient fibroblasts and these lysosomal alterations seemed to directly correlate to the time of onset of neurological disease symptoms." (PMID 27482815, 2016). "Notably, the Mgat5−/−:Npc1−/− mice were smaller than the single mutant Npc1−/− mice but appeared to be mobile and exhibited normal behavior prior to the onset of the neurological disease." (PMID 35563467, 2022). "NPC1 disease heterogeneity may explain the wide range in time until swallowing decline from neurological disease onset and the duration of neurological symptoms." (PMID 36064725, 2022). "During the neonatal period, infants with NPC1 may present with cholestatic liver disease, but after the neonatal period, progressive neurological disease dominates the clinical picture." (PMID 32731618, 2020). "The npc1 mutants model both the early liver and later neurological disease phenotypes of NPC1." (PMID 30135069, 2018).
neurological disease (continued). "A first in vivo study using Npc1 mutant mice claimed that repeated intra-peritoneal injections of vorinostat, an HDAC inhibitor, together with polyetheylene–glycol and CD slow down neurologic disease progression, but some controls were missing." (PMID 33256121, 2020). "Increased expression of C1qa does not appear to contribute to NPC1 neuropathology since neurological disease progression is not altered in Npc1−/−:C1qa−/− double mutant mice." (PMID 32731618, 2020).
cancer (24 papers, 2015 to 2025). A tumor composed of atypical neoplastic, often pleomorphic cells that invade other tissues. "We began by identifying Niemann-Pick C1 (NPC1) as a key cholesterol uptake gene linked to cancer progression through clinical data analysis." (PMID 41013744, 2025). "NPC1 deficiency led to reduced cancer growth and enhanced sensitivity to pyroptosis under pyroptotic stress." (PMID 41013744, 2025). "Niemann-Pick disease type C protein 1 (NPC1), classically associated with cholesterol transport and viral entry, has an emerging role in cancer biology." (PMID 39762312, 2025). "Together, these data demonstrate that NPC1 silencing acts on the mTOR pathway in association with decreased cancer cell viability, proliferation, and invasive capacity." (PMID 35884604, 2022). "In contrast, NPC1 knockdown, loss-of-function or overexpression of a dominant-negative NPC1 mutant that cannot bind cholesterol inhibited the proliferation, spreading and migration of several common cancer cell lines." (PMID 35806209, 2022). "We elucidated the mechanisms underlying NPC1-mediated growth regulation of cancer cells." (PMID 41013744, 2025). "Several studies have linked distinct NPC1 expression patterns with various types of cancer." (PMID 39707615, 2025). "Several observations have associated NPC1 expression patterns with cancer." (PMID 35806209, 2022). "Importantly, the target for the NPC-1 (TAA) was later identified as an aberrantly glycosylated MUC5AC variant (cancer-specific MUC5AC) that is different from native MUC5AC." (PMID 34205412, 2021). "In cancer cell lines activation of the protein kinase B (Akt)/mammalian target of rapamycin (mTOR) signalling pathway causes proteasomal-mediated degradation of NPC1." (PMID 34183444, 2021). "However, the relationship between NPC1 and cancer-associated cholesterol addiction, as well as the role of NPC1 in cancer-related cholesterol metabolic reprogramming remain largely unknown." (PMID 41013744, 2025). "NPC1 expression was highly elevated in human cancers and negatively correlated with patient survival." (PMID 41013744, 2025). "Inhibition or knockdown of NPC1 has been shown to reduce proliferation, spreading, and migration in several common cancer cell lines." (PMID 39707615, 2025). "This reprogramming of cholesterol metabolism through the upregulation of NPC1 expression was critical for the survival of cancer cells." (PMID 41013744, 2025). "These contrasting patterns of expression underscore the heterogeneity of NPC1’s role in different cancer types." (PMID 40881173, 2025). "To explore the role of NPC1 in human cancers, we knocked down NPC1 in three human cancer cell lines." (PMID 41013744, 2025). "Our findings revealed that NPC1 plays a crucial role in maintaining cholesterol homeostasis and protecting cancer cells from pyroptosis by facilitating LDL-mediated cholesterol uptake under pyroptotic stress." (PMID 41013744, 2025). "We conducted a series of in vitro and in vivo experiments using various human cancer cell lines and murine models to investigate the role of NPC1 in cancer progression." (PMID 41013744, 2025). "Despite its well-characterized function in cholesterol metabolism, research into NPC1’s role in cancer is limited." (PMID 39762312, 2025). "We observed that targeting NPC1 to reverse this metabolic reprogramming represents an effective strategy for killing cancer cells." (PMID 41013744, 2025). "Here we report that NPC1, a key player in cholesterol transport, protects cancer cells from pyroptosis across multiple cancer types." (PMID 41013744, 2025). "In this study, we analyzed cancer patient datasets and observed that high expression of NPC1 was closely associated with an aggressive behavior of tumors and poor survival rates, indicating that NPC1 may play an important role in tumor pathogenesis and serve as a promising therapeutic target." (PMID 41013744, 2025).
cancer (continued). "These included cancer stage (HR = 1.67, P < 0.01), T stage (HR = 1.64, P < 0.01), and NPC1 expression levels (HR = 1.09, P < 0.01) in the TCGA database." (PMID 40881173, 2025). "Taken together, these data indicate that cancer cells require NPC1 to enhance LDL uptake to resist pyroptosis." (PMID 41013744, 2025). "NPC1’s role in the biological mechanisms of cancer development is further supported by our GO and KEGG analyses, which indicated that the top 50 significant genes positively correlated with NPC1 are involved in functions critical to DNA replication." (PMID 40881173, 2025). "We analyzed The Cancer Genome Atlas (TCGA) datasets and found that NPC1 was significantly upregulated in tumors compared with adjacent tissues in 52% (12 out of 23) of TCGA cancer types, including HCC." (PMID 39762312, 2025). "Our research demonstrates that the NPC1 inhibitor U18666A can effectively target NPC1 to induce pyroptosis in cancer cells." (PMID 41013744, 2025). "We also found a statistically significant difference in NPC1 expression between low-grade (Grade 1) and high-grade (Grade 3) cancer groups." (PMID 40881173, 2025). "Our results not only substantiate the correlation between NPC1 expression levels and clinical outcomes in HCC but also position NPC1 as a potential independent prognostic biomarker for this aggressive cancer type." (PMID 40881173, 2025). "In summary, our results demonstrated a complex pattern of NPC1 expression in cancer, with significant upregulation in certain cancer types and downregulation in others." (PMID 40881173, 2025). "Expanding our analysis with the UALCAN database, we identified a significant overexpression of NPC1 in 17 distinct cancer types." (PMID 40881173, 2025). "Results showed that the expression of NPC1 was significantly elevated in a dose-dependent manner following nigericin treatment, and the phenomenon was observed in various cancer cell lines." (PMID 41013744, 2025). "Future research is needed to further elucidate the full scope of NPC1’s functions in cancer, particularly its interactions with other signaling pathways." (PMID 39762312, 2025). "Reintroducing NPC1 (P691S) restored TGFBR1 levels and cell migration, highlighting a cholesterol-independent function for NPC1 in cancer progression." (PMID 39762312, 2025). "Analysis of cancer patient datasets revealed that higher NPC1 expression correlated with poorer patient survival, indicating that NPC1-regulated LDL-cholesterol uptake plays a critical role in tumor progression." (PMID 41013744, 2025). "This places NPC1 at the forefront as a potential therapeutic target in cholesterol trafficking and a candidate for cancer therapy." (PMID 40881173, 2025). "It remains to be seen how common is NPC1 upregulation is cancers that use macropinocytosis for cholesterol uptake, and when the first clinically approved macropinocytosis inhibitors will be developed." (PMID 39243069, 2024). "Invasion assays utilizing cancer cell spheroids and tumor organoids revealed an invasion promoting role of NPC1 and extracellular cholesterol." (PMID 37420029, 2023). "Vice versa, upregulation of Rab7-GTP levels not only rescued cholesterol accumulation in NPC1 mutant cells, but was also associated with LDL-inducible migration and invasion of cancer cells." (PMID 35806209, 2022). "Together, these data demonstrate the novel finding of cholesterol auxotrophy in TNBC cancer cells, which correlates with NPC1 protein expression." (PMID 35884604, 2022).
cancer (continued). "Given the role of mTOR in cancer and its physical interaction with the lysosome and NPC1, the western blot was used to evaluate how NPC1 silencing affects mTOR signaling." (PMID 35884604, 2022). "In addition, StARD3 has been linked to cholesterol overload in mitochondria in NPC1 deficiency, which supported roles for StARD3 in LE/Lys-Chol transport to mitochondria for steroidogenesis, mitochondrial well-being and energy production, all anti-apoptotic properties in cancer settings." (PMID 35806209, 2022). "Literature evaluating NPC1 in cancer is extremely limited, with few studies showing elevated NPC1 in certain cancers, and implicating NPC1 in cell invasion and cell growth." (PMID 35884604, 2022). "In support of this, NPC1 mutant-like cancer cell models revealed changes in the plasma membrane order, reinforcing direct or indirect cell surface delivery of LE/Lys-Chol to provide structural integrity of membrane microdomains and signalling complexes." (PMID 35806209, 2022). "Previous work and data presented here, using genetic and pharmacological NPC1 inhibition or AnxA6 overexpression, demonstrated that blocking LE-Chol export interfered with the migratory, but also invasive behaviour of several cancer cell lines." (PMID 35022465, 2022). "Two main studies have used recombinant chimeric NPC1 antibodies prepared in Chinese hamster ovary cells (NPC-1C) to identify cancer-specific MUC5AC." (PMID 34205412, 2021). "The monoclonal antibodies elicited with TAA, also known as NPC1, were used to test vaccines in other cancers like melanoma, but the results were disappointing." (PMID 34205412, 2021). "Accordingly, NPC1 and cholesterol trafficking are also under evaluation as potential therapeutic targets in cancer." (PMID 32235572, 2020). "Three DEG were also statistically significant after FDR correction: Npc1 in cellular processes and Ifitm10 and Sox17 in genes involved in cancer." (PMID 29950665, 2018). "To determine whether inhibiting NPC1 can be therapeutic against cancers, we used the NPCI specific inhibitor U18666A to treat ARP-1, HepG2, and SKOV3 cells." (PMID 41013744, 2025). "Furthermore, colony-forming assay indicated a diminished colony formation ability in various cancer cells following NPC1 depletion." (PMID 41013744, 2025). "In this study, we identified NPC1 as a key protein for LDL uptake in cancer cells." (PMID 41013744, 2025). "Our data indeed reveal marked heterogeneity in NPC1 expression across cancer types, with pronounced upregulation in pancreatic, liver, and other malignancies, while showing reduced expression in six cancer types." (PMID 40881173, 2025). "However, our study highlights an alternative, cholesterol-independent mechanism by which NPC1 interacts with TGFBR1 to promote cancer progression." (PMID 39762312, 2025). "This study reveals that NPC1 may be a potential therapeutic target for the treatment of human cancers." (PMID 41013744, 2025). "Thus, our research reveals that NPC1 protects cancer cells from pyroptosis by reprogramming tumor cholesterol metabolism and identifies NPC1 as a therapeutic target for human cancer." (PMID 41013744, 2025). "Our findings, along with those from previous studies, targeting NPC1 might be beneficial in cancer treatment owing to its role in cholesterol handling." (PMID 40881173, 2025). "In contrast, NPC1 expression was notably lower in six cancer types." (PMID 40881173, 2025). "Moreover, NPC1 inhibitor U18666A induced cancer cell pyroptosis and was highly therapeutic, either alone or combined with chemotherapeutics, against human hematologic and solid cancers in xenograft mouse models." (PMID 41013744, 2025). "As NPC1 is commonly and highly expressed in human cancers, our results suggest that NPC1 may be a potential therapeutic target that warrants further investigation." (PMID 41013744, 2025). "Additionally, analysis of the TCGA dataset revealed that NPC1 expression was upregulated across multiple cancer types." (PMID 41013744, 2025).